FGF21 (fibroblast growth factor 21)
Diseases named in the same sentence as FGF21 in open-access papers (continued):
Sharing a sentence is not in itself a finding about the gene and the disease.
steatosis (continued). "FGF21 administration was ineffective to improve hyperinsulinemia and steatosis in Ay females." (PMID 34943946, 2021). "Additionally, we also analyzed serum FGF21, a regulator of hepatic metabolic pathways, to improve the steatosis and inflammation." (PMID 33808318, 2021). "Our previous studies indicated that FGF21 played a key role in preventing the development of the major characteristics of NASH: steatosis, inflammation, and metabolic syndrome, however, the FGF15/19 mediated-FGFR4 signaling worsened NASH and even contributed to the NASH-HCC transition." (PMID 34326695, 2021). "Serum FGF21 regulates hepatic metabolic pathways to improve steatosis and inflammation." (PMID 34768813, 2021). "It is still not fully understood if a direct action on hepatocytes contribute to the positive effect of FGF19 and FGF21 on steatosis, but overexpression of an inactive KLB mutant interestingly induces intracellular lipid accumulation in HepG2 and Huh7 cells in vitro." (PMID 33414764, 2020). "The main features of NASH pathology in metabolic models, i.e., steatosis, mild inflammation, and mild fibrosis have all been found to be improved by treatments with FGF21, as well as FGF19 and analogues thereof which may partly be driven by a decrease in BW." (PMID 33414764, 2020). "Additional morphological and biochemicalstudies are needed to find out whether FGF21 initiates (orpromotes) steatosis in Ay-female mice." (PMID 33659800, 2020). "The effect of FGF21 on steatosis in the MCD and CDA-HFD models may be linked to FGF21’s ability to increase FA oxidation or to decrease DNL." (PMID 33414764, 2020). "The results indicated that stepwise increments in BMI (B = 0.174, P = 0.033), γ-GT (B = 0.368, P < 0.001), TG (B = 0.180, P = 0.035), and log-transformed FGF-21 levels (B = 0.273, P = 0.002) were significantly correlated the steatosis grade of obese and overweight children (P < 0.05)." (PMID 31750276, 2019). "Notably, baseline M30 and M65ED levels were significantly higher in subjects who had suspected NASH at follow-up reassessment than those who sustained simple steatosis, while FGF21 level were similar in these two groups." (PMID 28698650, 2017). "Serum FGF21 levels are increased in chronic HC (CHC) patients with steatosis and are associated with the steatosis grade, which may be a useful diagnostic marker for determining hepatic steatosis in CHC." (PMID 26483756, 2015). "Hepatic Fgf21 expression, ketogenesis, and steatosis are greatly induced in mice fasted for 24 h." (PMID 23874946, 2013). "The forced increase in NEFA level from adipocytes due to FGFR1 deficit under prolonged starvation, likely in part resulted in the observed compensatory increases of hepatic and serum FGF21 through hepatic PPARα, and the elevated hepatic lipogenesis and steatosis as well." (PMID 23106963, 2012). "Additionally, new therapies targeting fibrosis, such as FGF21 analogs, are in clinical trials and may offer benefits in preventing progression from simple steatosis to more advanced liver disease." (PMID 39605938, 2024). "However, among the limited number of genes showing both gene expression and methylation variation, Cysteine Sulfinic Acid Decarboxylase CSAD and FGF21 were previously noted in two independent studies to be able to mitigate lipid accumulation and steatosis in HFD-treated mice." (PMID 39770043, 2024). "Moreover, because FGF21 is known to modulate the hepatic metabolic pathway to suppress steatosis, the observed reduced FAS expression and lipid accumulation by E2 and coumestrol in the liver might be associated with increased FGF21 production." (PMID 36839308, 2023). "Notably, the protein expression of FGF21, which is a key regulator in maintaining whole-body energy balance and protecting the liver from steatosis, was markedly decreased in the liver and WAT following ovariectomy, but was restored by E2 and coumestrol treatments." (PMID 36839308, 2023).
steatosis (continued). "Lack of FGF21 also reduces hepatic FA oxidation in ko mice fed a methionine-choline deficient (MCD) diet which is accompanied with more severe steatosis, peroxidative damage, inflammation, endoplasmic reticulum stress, and fibrosis when compared to wild-type mice." (PMID 33414764, 2020). "Enlarged liver under the action of FGF21 infemale Ay-mice may indicate the development of steatosis.Simultaneous decrease in catabolic (lipolysis, glycolysis) andanabolic (lipogenesis, gluconeogenesis) processes can suggestdecreased metabolism in the liver of Ay-females." (PMID 33659800, 2020). "That is, chronically treated ob/ob mice exhibit reduced circulating and liver fatty acids and increased circulating FGF21 and adiponectin as well as a significant suppression of the de novo hepatic lipogenic enzymatic cascade, providing an explanation for the reversal of steatosis." (PMID 30374109, 2018). "However, very prominent and severe steatosis and fibrosis were observed in FGF21-KO-LDC mice." (PMID 29107287, 2017). "We next tested whether FGF21 overexpression ameliorates hepatic steatosis of Creb3l3−/− mice." (PMID 27301791, 2016). "Its effects extend to hepatic improvement, with decreased liver fat content and fibrosis-related markers such as fibroblast growth factor 21 (FGF-21) and procollagen type III (Pro-C3), suggesting a potential to reverse steatosis and early fibrosis." (PMID 41235339, 2025). "Overall, we investigated hepatic expression of FGF21 in regards to gender and clinical characteristics, and considered histological scores of NAS, steatosis, ballooning, lobular inflammation and fibrosis." (PMID 39962359, 2025). "Compared with lean controls, serum FGF21 levels were increased in patients with MASLD, especially in those with severe steatosis." (PMID 40496439, 2025). "Elevated levels of fibroblast growth factor 21 (FGF21) and leukocyte cell-derived chemotaxin 2 (LECT2) have been correlated with steatosis severity and hepatic inflammation." (PMID 41011683, 2025). "Fibroblast growth factor 21 (FGF21) analogs, such as efruxifermin, and acetyl-CoA carboxylase (ACC) inhibitors show promise in reducing steatosis and fibrosis." (PMID 40136408, 2025). "Studies have confirmed that FGF21 knockout mice with NAFLD have more severe ER stress and steatosis in the liver than wild-type NAFLD mice." (PMID 39334685, 2024). "Therefore, induction of the PPARα-FGF21 axis in a ketogenic state could decrease steatosis." (PMID 36896171, 2023). "Recent studies have shown that circulating levels of FGF21 positively correlate with the severity of MASLD and the steatosis degree." (PMID 37998747, 2023). "Among them, FGF-21 has already been proposed as a biomarker in NAFLD, with predictive relevance of hepatic damage as a result of steatosis." (PMID 37999215, 2023). "Nonetheless, we could identify a steatosis related phenotype with the high steatosis lines S11 and S08 tending to have low expression of genes involved in lipid export, fat and cholesterol synthesis as well as in gluconeogenesis, β-oxidation and FGF21 signalling." (PMID 33372064, 2021). "In summary, both FGF21 and FGF19 analogues decrease steatosis, inflammation and fibrosis in various NASH models." (PMID 33414764, 2020). "Mice fed a MCD diet presented NASH-like features such as steatosis and inflammation, assessed by the histopathological evaluation of the NAS score, intrahepatic TG accumulation, elevated ALT and increased Fgf21 mRNA levels." (PMID 30405191, 2018). "The AUROC value of the CBP was 0.94 (95% CI, 0.92–0.96), compared to CK-18 or FGF-21 assay, which showed the most significant ability to distinguish NASH from simple steatosis." (PMID 28326329, 2017). "In Fgf21 KO mice, MCD diet induces more severe steatosis, fibrosis, inflammation, and peroxidative damage." (PMID 26594197, 2015). "Fibroblast growth factor 21 (FGF21) serum levels are high in NAFLD patients and its expression in the liver increases with the steatosis grade." (PMID 23209914, 2012).
steatosis (continued). "Our study also showed that a chronic activation of PPARα improves steatosis independent of FGF21 induction." (PMID 40815899, 2025). "Furthermore, there were robust correlations between FGF21 levels and the NAS, with positive relationships for lobular inflammation, steatosis, and fibrosis." (PMID 40943431, 2025). "Additionally, the decrease in ATP content and ATPase activity, along with the downregulation of FGF21, p-AMPK, and PGC-1α were observed in both HFD-induced liver injury and NaOL-induced hepatocyte steatosis." (PMID 39161898, 2024). "Even in the absence of chronic hepatitis infections, FGF-21 has been described as a metabolic marker, correlating with the degree of steatosis." (PMID 37999215, 2023). "We speculate that increased miR-22 blunts hepatic FGF21 synthesis and secretion in children with NAFLD, and therefore promotes worsening of steatosis." (PMID 35498403, 2022). "On the other hand, in a previous study on patients with NAFLD, no changes in FGF-21 levels were observed depending on the degree of steatosis and oxidative damage markers." (PMID 35745238, 2022). "FGF21 analogs and agonists are a major target for the treatment of NAFLD with several molecules in late stage clinical development and promising results on the reduction of steatosis and inflammation." (PMID 36406708, 2022). "It is not known if FGF21 is unable to improve liver health in only Ay females or also in females with other models of steatosis." (PMID 34943946, 2021). "Strikingly, commensurate with the reduced NEFA and increased FGF21 and adiponectin levels in the serum, livers of mBP3 expressing ob/ob mice displayed a significant reduction of steatosis and were almost indistinguishable microscopically from healthy livers." (PMID 30374109, 2018). "Furthermore, the AUROC of CBP was 0.94 (95% CI, 0.92–0.96), compared to CK-18 or FGF-21 assay, which showed the most significant ability to distinguish NASH from simple steatosis." (PMID 28326329, 2017). "The hepatic overexpression of FGF21 in liver-specific SIRT1 knockout mice increases the expression of genes involved in fatty acid oxidation, thereby decreasing fasting-induced steatosis, reducing obesity, increasing energy expenditure, and promoting the browning of white adipose tissue." (PMID 27148532, 2016). "We propose an axis of hepatocyte-adipocyte cooperation mediated by hepatocyte FGF21 and adipocyte FGFR1 that serves to protect and mete out lipid reserves systemically while protecting the liver against excessive steatosis and damage under metabolic extremes and general hepatic stress." (PMID 23106963, 2012). "We hypothesize that the lack of correlation between FGF-21 and steatosis may be due to the presence of a hierarchy of insults influencing FGF-21 levels." (PMID 37999215, 2023). "Promising biomarkers, which are related to NASH and may help differentiate steatosis from steatohepatitis, are cytokeratin-18 (CK-18), the terminal peptide of procollagen III (PIIINP), IL-6, TNF-α, the chemokines MCP-1 and RANTES, and fibroblast growth factor 21 (FGF21)." (PMID 35877216, 2022). "However, this did not translate in a lower rate of steatosis for animals that received FGF21." (PMID 36406708, 2022). "In addition, Ad-Fgf21-injected hPPARαPAC mice no longer had steatosis and focal necrosis." (PMID 25991671, 2015). "In a protein–protein interaction network, IGSF9 was found to have a central position, being correlated to FGF21, CES1, MAMDC4, and afamin (AFM) in PLHIV with steatosis, and to AFM and GHR in those without steatosis." (PMID 39426127, 2024). "Soy isoflavone intake led to a decrease in ALT, AST, CAP score, steatosis grade and an increase in the level of fetuin A. However, no significant changes were observed in the fibrosis grade and serum levels of GGT and FGF-21." (PMID 38429385, 2024).
steatosis (continued). "In a prospective study of a Chinese population, both CK-18 and FGF21 were elevated in NAFLD, though baseline FGF21, but not the CK18 level, was an independent predictor for the development of simple steatosis." (PMID 37189422, 2023). "Except steatosis, no other obvious pathomorphological changes were observed in the liver tissues from either OVX or OVX+FGF21 LKO mice." (PMID 37834368, 2023). "Consistently, in our study, FGF19 showed negative correlation with steatosis and enhanced the predictiveness of MSI-S, demonstrating the second highest influence on FGF21." (PMID 35663311, 2022). "On the other hand, while available evidence seems to suggest that FGF21 patterns may have promising relevance to the assessment of NAFLD status, it alone cannot fully account for differences between no steatosis, simple steatosis, or advanced stages." (PMID 33071964, 2020). "Interestingly, mice with neutropenia, defective neutrophil infiltration or lacking elastase were protected against steatosis correlating with lower JNK activation, reduced Bmal1 and increased FGF21 expression, together with decreased lipogenesis in the liver." (PMID 33287957, 2020). "To determine if FGF21, CK18 and CK18 M30 expression levels in liver were changed along with liver pathological manifestations and apoptosis marker, we examined the markers using immunohistochemistry staining in liver tissues from patients without NAFLD, patients with simple steatosis or with NASH." (PMID 28698650, 2017).
atherosclerosis (98 papers, 2013 to 2026). A disease characterized by the build-up of fatty material and calcium deposition in the arterial wall resulting in partial or complete occlusion of the arterial lumen. "FGF21 deficiency can lead to systemic inflammation that promotes the progression of atherosclerosis." (PMID 39558976, 2024). "Fibroblast Growth Factor-21 (FGF21), a novel hormone with anti-atherosclerotic properties, is associated with the presence of atherosclerosis and reduces plaque formation in experimental animals." (PMID 39108652, 2024). "In a High-fat diet (HFD)-induced obese C577BL/6J MICE, empagliflozin increased plasma levels of Fibroblast Growth Factor 21 (FGF21), protecting the cells from damage caused by atherosclerosis-associated oxidative stress." (PMID 36148061, 2022). "In apolipoprotein E–/– mice, FGF-21 deficiency results in accelerated atherosclerosis and premature death, along with hypoadiponectinemia and hypercholesterolemia." (PMID 35186330, 2022). "This is a cross-sectional study that would limit determination of a causal relationship between FGF21, sex, and subclinical atherosclerosis." (PMID 33996935, 2021). "The sex–racial patterns in the mechanisms by which FGF21 causes subclinical atherosclerosis needs to be explored in larger population-based studies and mechanistically studied in greater detail." (PMID 33996935, 2021). "Background and Aims: Fibroblast growth factor 21 (FGF21), an emerging metabolic hepatokine, is associated with atherosclerosis." (PMID 33996935, 2021). "Administration of FGF21 has been reported to improve atherosclerosis risk factors, including blood glucose concentrations, blood lipids, and weight in animal models using rodents and primates." (PMID 32957703, 2020). "We aimed to investigate the effect of an FGF21 analogue (LY2405319) on the development of atherosclerosis and its associated parameters." (PMID 32957703, 2020). "As there is difference in atherosclerosis susceptibility between humans and rodent, further studies are needed to confirm the therapeutic role of FGF21 against atherosclerosis in humans or large humanoid animals such as pigs." (PMID 32227589, 2020). "Clinical studies have shown elevated levels of circulating FGF21 in patients with atherosclerosis or those at high risk of atherosclerosis." (PMID 31498116, 2019). "We used an in vitro and in vivo approach to study the role of FGF21 in the progression of atherosclerosis-associated apoptosis." (PMID 30157856, 2018). "Preliminary clinical studies reported that serum FGF21 levels were increased in patients with atherosclerosis and in patients with a high risk of atherosclerosis." (PMID 30157856, 2018). "As an important adipokine, fibroblast growth factor 21 (FGF21) has been demonstrated to be associated with atherosclerosis and coronary artery disease (CAD)." (PMID 30185439, 2018). "Mechanistic study indicated that FGF21-induced prevention of atherosclerosis was associated with suppression of endoplasmic reticulum stress-mediated apoptosis in apoE−/− mice (C57BL/6J background)." (PMID 27247947, 2016). "Clinical studies showed that increased circulating FGF21 levels were discovered in atherosclerotic patients or the individuals with high risk of developing atherosclerosis." (PMID 27247947, 2016). "In recent clinical and preclinical studies, CVDs have been closely associated with serum FGF21 which increased in the patients with atherosclerosis, coronary heart disease, myocardial ischemia, cardiac hypertrophy, and diabetic cardiomyopathy." (PMID 27247947, 2016). "Hence, elevated serum FGF-21 associated with atherosclerosis likely reflects this adaptive mechanism." (PMID 35186330, 2022). "Loss of FGF21 accelerates the plaque formation and the development of atherosclerosis in apoE KO mice, and administration with recombinant human FGF21 protein strongly attenuates the development of atherosclerosis in apoE KO mice by suppression of cholesterol synthesis and production of adiponectin." (PMID 35463746, 2022).